CYLD (CYLD lysine 63 deubiquitinase)
Diseases named in the same sentence as CYLD in open-access papers (continued):
Sharing a sentence is not in itself a finding about the gene and the disease.
periodontitis (3 papers, 2021 to 2025). An acute or chronic inflammatory process that affects the tissues that surround and support the teeth. "Furthermore, CYLD has been reported to ameliorate alveolar bone loss in mouse models of periodontitis by regulating the number and activity of osteoclasts, as well as the genes related to osteogenesis and osteoclastogenesis in alveolar bones." (PMID 38322269, 2024). "Further investigation revealed that compared with wild‐type mice, CYLD knockout mice with periodontitis manifested an increased number of osteoclasts, reduced osteogenesis and subsequently aggravated alveolar bone loss." (PMID 39626954, 2025). "Research further showed a significant decrease in CYLD protein levels in the inflamed gingival tissue of mice with periodontitis compared to healthy controls, suggesting a potential regulatory role of CYLD in periodontitis." (PMID 39626954, 2025). "CYLD can also modulate the NF-κB signaling pathway, which plays a crucial role in the inflammatory response and osteoclast mediation in periodontitis." (PMID 38322269, 2024). "Recent studies have shed light on the contrasting roles of USP5 and CYLD in periodontitis, offering potential avenues for therapeutic interventions." (PMID 38322269, 2024). "Therefore, the targeted regulation of CYLD presents a burgeoning avenue for periodontitis treatment." (PMID 39626954, 2025). "Meanwhile, DUBs, including OTUD1, A20, CYLD, UCH‐L1 and USPs, also broadly modulate periodontitis progression by regulating signalling pathways such as NF‐κB, Wnt/β‐catenin, NLRP3, and BMP2." (PMID 39626954, 2025). "Given the role of these DUBs in limiting inflammation, our findings suggest that CYLD, A20 and OTULIN might be involved in the pathogenesis of periodontitis and might act as potential therapeutic targets to treat periodontitis." (PMID 34092220, 2021). "Our findings suggest that CYLD, A20 and OTULIN might play a role in the progression of periodontitis." (PMID 34092220, 2021).
psoriasis (3 papers, 2016 to 2026). An autoimmune condition characterized by red, well-delineated plaques with silvery scales that are usually on the extensor surfaces and scalp. "Recently, several CYLD variants have been related to the development of autoimmune diseases and psoriasis." (PMID 37893484, 2023). "In this study, the expressions of A20, CYLD and Cezanne were examined by quantitative real time-PCR and immunophenotype by flow cytometry in 82 patients with psoriasis and 147 healthy individuals." (PMID 37893484, 2023). "Recently, two SNPs (rs4785452 and rs12925755) in the CYLD gene have been reported to link to autoimmune diseases and psoriasis." (PMID 37893484, 2023). "Despite the well-recognized role of the deubiquitinase CYLD in the pathogenesis of tumors and certain inflammatory diseases, its specific function and regulatory mechanisms in psoriasis remain unclear." (PMID 41559325, 2026). "Unlike A20 and CYLD, the effects of Cezanne on the pathogenesis of psoriasis are not well known." (PMID 37893484, 2023).
pulmonary fibrosis (3 papers, 2020 to 2024). Chronic progressive interstitial lung disorder characterized by the replacement of the lung tissue by connective tissue, leading to progressive dyspnea, respiratory failure, or right heart failure. "Strikingly, CYLD deficiency significantly exacerbated BLM-induced pulmonary fibrosis as demonstrated that the pulmonary interstitial thickness and cell density was enhanced in the cyld−/− knockout mice." (PMID 39122680, 2024). "Moreover, we found that CYLD is downregulated during pulmonary fibrosis, and cyld−/− knockout mice were susceptible to BLM-induced pulmonary fibrosis, suggesting the significance of CYLD in lung function." (PMID 39122680, 2024). "Mechanistic study reveals that downregulation of CYLD underlies the crosstalk between EMT and ciliary homeostasis by inactivating histone deacetylase 6 (HDAC6) during pulmonary fibrosis." (PMID 39122680, 2024). "In the normal conditions, CYLD inactivates HDAC6 to promote primary ciliary homeostasis as well as inhibit EMT program; however, during pulmonary fibrosis, CYLD deficiency relieves its inhibitory interaction with HDAC6, thereby leading to primary disassembly and the EMT program." (PMID 39122680, 2024). "A previous study reported CYLD inhibits lung fibrosis development via the TGF-β signaling pathway." (PMID 32708712, 2020). "Having identified the role of CYLD in EMT program and primary cilia, we next generated CYLD knockout mice to examine its influence on pulmonary fibrosis." (PMID 39122680, 2024). "Collectively, these results identify a pivotal role for the CYLD/HDAC6 signaling in regulating the reciprocal interplay between the EMT program and ciliary homeostasis during pulmonary fibrosis." (PMID 39122680, 2024). "Here, we reveal a critical role for cylindromatosis (CYLD) in reciprocally linking the EMT program and ciliary homeostasis during pulmonary fibrosis." (PMID 39122680, 2024). "In this study, we identify a critical role for CYLD/HDAC6 signaling in regulating the reciprocal interplay between the EMT program and primary cilia during pulmonary fibrosis." (PMID 39122680, 2024). "Our previous study and others revealed that CYLD is a HDAC6 inactivator, we speculate that CYLD regulates EMT program and ciliary homeostasis by inactivating HDAC6 during pulmonary fibrosis." (PMID 39122680, 2024).
Sepsis (3 papers, 2024 to 2025). Sepsis is defined as life-threatening organ dysfunction caused by a dysregulated host response to infection. "Absence or deficiency of CYLD results in uncontrolled inflammatory responses that significantly exacerbate the severity of sepsis." (PMID 39720715, 2024). "In conclusion, CYLD alleviated sepsis-induced inflammation by interacting with the TRAF6/sNASP axis." (PMID 40108019, 2025). "To verify the functional role of CYLD as an attenuator of LPS stimulation in an animal model, we injected either Ad-CYLD WT or Ad-CYLD mut into a sepsis-induced murine ALI model." (PMID 40108019, 2025). "In sepsis, cytoplasmic DUBs (CYLD and A20) ubiquitylize the K63 chain of key proteins, such as RIPK1 and NEMO, by removing the inhibit overactivation of NF-κB and MAPK signaling, thereby reducing cytokine release and inflammatory spread." (PMID 39720715, 2024). "Therefore, our study discovered a new anti-inflammatory mechanism of CYLD in sepsis-induced lung inflammatory responses and identified the CYLD-TRAF6/sNASP axis as a potential therapeutic target for treating sepsis-induced ALI." (PMID 40108019, 2025). "In vivo, mice infected with a recombinant adenovirus carrying a gene encoding CYLD wild-type (Ad-CYLD WT), but not a mutation, showed markedly attenuated sepsis-induced ALI, with significant reductions in the production of proinflammatory cytokines." (PMID 40108019, 2025). "These discoveries further confirmed that CYLD might serve as a potential drug target for treating sepsis-induced pneumonia." (PMID 40108019, 2025). "These discoveries indicated the inhibitory effect of CYLD in sepsis-induced inflammatory responses and may be a potential drug target for treating pneumonia due to bacterial infection." (PMID 40108019, 2025). "The protein expression levels of four upregulated necroptosis‐related DEGs (PYGL, TNF‐α, CYLD and FADD) were significantly higher in the sepsis group than in the control group in all three cells, whereas the TLR3 level was only significantly higher in HUVEC cells." (PMID 40318009, 2025). "Regarding the prediction of mortality in patients with sepsis, the levels of corresponding proteins to the three upregulated necroptosis‐related genes showed excellent or considerable accuracy (AUC; TNF‐α = 0.904, PYGL = 0.851 and CYLD = 0.846)." (PMID 40318009, 2025).
squamous cell carcinoma (3 papers, 2014 to 2020). A carcinoma arising from squamous epithelial cells. "Previous reports indicate that functional inactivation of CYLD promotes the metastasis in squamous cell carcinomas." (PMID 32708712, 2020). "Another finding worth noting is that hypoxia stimulates human papilloma virus-encoded E6 protein to promote ubiquitination and proteasomal degradation of CYLD in human papilloma virus-positive squamous cell carcinoma cell lines." (PMID 25071012, 2014). "Only five CYLD-mutant cases (7%) showed nonbasaloid conventional squamous cell carcinoma histology (median TMB = 5.2 mut/Mb), and a single CYLD-mutant case showed transitional cell carcinoma-like histology." (PMID 32461623, 2020).
Streptococcus pneumoniae infection (3 papers, 2013 to 2025). "The absence of CYLD protects mice from ALI caused by lethal Streptococcus pneumoniae infections by suppressing expression of plasminogen activator inhibitor (PAI)−1." (PMID 40108019, 2025).
T-cell leukemia (3 papers, 2014 to 2018). A malignant disease of the T-lymphocytes in the bone marrow, thymus, and/or blood. "In T cell leukemia, Notch signaling through one of its target gene, Hes1, sustains NF-κB activation by repressing expression of deubiquitinase CYLD." (PMID 29889863, 2018). "Conversely, CYLD expression in T-cell leukemia was regulated by transcriptional repression by Hes1." (PMID 24495516, 2014).
acute lung injury (2 papers, 2013 to 2025). A condition of lung damage that is characterized by bilateral pulmonary infiltrates (pulmonary edema) rich in neutrophils, and in the absence of clinical heart failure. "(2007) showed that CYLD deficiency protected mice from S. pneumoniae pneumolysin (PLY)-induced Acute lung injury (ALI) and lethality." (PMID 39958342, 2025). "An important negative impact of CYLD on p38-dependent protective PAI-1 induction has recently been shown in severe Streptococcus pneumoniae-induced acute lung injury." (PMID 23825949, 2013).
acute myeloid leukemia (2 papers, 2023 to 2025). Acute myeloid leukemia (AML) is a group of neoplasms arising from precursor cells committed to the myeloid cell-line differentiation. "The expression levels of A20 are negatively associated with macrophage apoptosis, whereas CYLD stimulates macrophage apoptosis in acute myeloid leukemia." (PMID 40896706, 2025). "Our recent study indicates that CYLD inhibits maturation and promotes apoptosis and phagocytosis of macrophages in patients with acute myeloid leukemia." (PMID 40896706, 2025).
adenoid cystic carcinoma (2 papers, 2021 to 2022). A malignant tumor arising from the epithelial cells. "No CYLD-mutant or CYLD-wildtype cases demonstrated the NFIB-MYB gene fusion typical of adenoid cystic carcinoma." (PMID 32892208, 2021).
adnexal skin tumors (2 papers, 2009 to 2021). "Cylindromatosis (CYLD) is a deubiquitinase (DUB) enzyme that was initially characterized as a tumor suppressor of adnexal skin tumors in patients with CYLD syndrome." (PMID 34201751, 2021).
basal cell adenocarcinomas (2 papers, 2020 to 2021). "A recent study identified CYLD mutations within both basal cell adenomas and basal cell adenocarcinomas, perhaps accounting for some of the morphologic overlap with the cases in this current study." (PMID 32892208, 2021). "Interestingly, the basal cell adenomas and carcinomas harbor mutations of CYLD in exons 9–11, while only basal cell adenocarcinomas harbor CYLD mutations involving exons 12–20, corresponding to the ubiquitin-specific hydrolase domain." (PMID 32461623, 2020). "Another study found CTNNB1 mutations in basal cell adenomas and, among other alterations, focal CYLD deletion and biallelic inactivation of NFKBIA in a case of basal cell adenocarcinoma." (PMID 32892208, 2021).
basaloid anal carcinomas (2 papers, 2020 to 2021). "In our assessment, basaloid carcinoma of the anus is closely analogous to the CYLD-mutant oropharyngeal carcinomas described in this study." (PMID 32892208, 2021).
cerebral malaria (2 papers, 2017 to 2025). A sequestration of Plasmodium falciparum in the brain, which can cause coma and/or seizures. "Depletion of CYLD in T cells attenuates T-cell responses, prevents blood–brain barrier disruption, and protects mice from experimental cerebral malaria." (PMID 39958342, 2025).
COVID-19 (2 papers, 2021 to 2022). A disease caused by infection with severe acute respiratory syndrome coronavirus 2. "CYLD is upregulated in both COVID-19 and cardiomyopathy and was found to correlate with the activation of FGFR2, an important promoter of inflammation, and TXA2, a gene that is upregulated in platelets (Figure A2A)." (PMID 34071557, 2021). "Finally, CYLD lysine 63 deubiquitinase (CYLD) was correlated with multiple identical pathways for both COVID-19 samples and ICM samples." (PMID 34071557, 2021).
dermatitis (2 papers, 2020 to 2024). An inflammatory process affecting the skin. "A custom NGS panel targeted sequencing was used to screen the pathological mutation in more than 596 genes related to common hereditary dermatosis to screen the pathological mutation of the proband, including the CYLD gene." (PMID 32783365, 2020). "Further to this, a role for CYLD in myeloid mononuclear phagocytes is implicated in the Sharpincpdm dermatitis phenotype, although whether the function of CYLD is required in the LCs and/or infiltrating immune cells remains unclear." (PMID 38156288, 2024). "Moreover, conditional deletion of CYLD, a pro-death deubiquitinase, in myeloid mononuclear phagocytes completely rescues the Sharpincpdm dermatitis phenotype." (PMID 38156288, 2024).
diffuse large B-cell lymphoma (2 papers, 2017 to 2023). "A study reported that, as novel MALT1 inhibitors, β-lapachone analogs exhibited potent antiproliferative activity and inhibited the cleavage of CYLD mediated MALT1; this may be a promising therapeutic target for the treatment of aggressive subtype of diffuse large B-cell lymphoma." (PMID 29259980, 2017).
esophageal cancer (2 papers, 2016 to 2020). A primary or metastatic malignant neoplasm involving the esophagus. "This study provides insight into the mechanisms underlying the reciprocal regulation between STAT3 and miR-181b to regulate the proliferation of esophageal cancer cells with cancer stem-like cells properties via the CYLD pathway." (PMID 27189061, 2016).
ischemic stroke (2 papers, 2017 to 2018). A stroke disorder caused by obstruction of blood flow to the brain, due to thrombotic (local blood clot formation) or embolic (due to a blood clot or other material traveling from another site) event. "However, how CYLD modulates acute inflammatory injury induced by ischemic stroke is limited so we studied a rat model of MCAO and measured CYLD expression after focal cerebral ischemia/reperfusion." (PMID 29163038, 2017). "Thus, neuronal CYLD was essential for EA-induced inhibition of the NF-κB signaling pathway after ischemic stroke." (PMID 29163038, 2017). "This may indicate that upregulation of neuronal CYLD by EA has an anti-inflammatory role in ischemic stroke." (PMID 29163038, 2017). "Our previous studies demonstrated that other deubiquitinase, such as the zinc finger protein A20 and cylindromatosis (CYLD), functioned as negative regulators of NF-κB and were involved in regulating neuroinflammation through depressing neuronal NF-κB activity in ischemic stroke." (PMID 29544517, 2018).
Klebsiella Infections (2 papers, 2025). Infections with bacteria of the genus KLEBSIELLA. "In deubiquitinase cylindromatosis (CYLD) negative host cells Klebsiella infection quickly followed by production of IL8 this happens because in (CYLD) positive cells K. pneumoniae hijacked the (CYLD) thus inhibits NF-κB signaling." (PMID 41333289, 2025).
liver disease (2 papers, 2020 to 2022). "In liver disease, CYLD acts as an important regulator of hepatocyte homeostasis by preventing progressive fibrosis, inflammation, tumor necrosis factor (TNF) production, and expansion of hepatocyte apoptosis towards the central veins." (PMID 35579924, 2022). "Dysregulated TNFR1 signalling also contributes to development of liver disease and cancer, and liver-specific deletion of the M1/K63-specific DUB CYLD causes TNFR1-mediated hepatitis and HCC." (PMID 32231246, 2020). "In addition, CYLD is a protective molecule against liver disease which contributes to hepatic homeostasis and restoration upon liver injury." (PMID 35579924, 2022). "We therefore conclude that the cellular aberrations leading to liver disease in Otulin∆hep mice are independent of TNFR1 signalling and thus distinct from the pathology in CYLD-deficient livers." (PMID 32231246, 2020).
liver fibrosis (2 papers, 2019 to 2022). "We have recently demonstrated that disruption of Notch signaling by myeloid-specific RBP-J knockout attenuated liver fibrosis by compromising macrophage activation through the CYLD-NF-κB pathway." (PMID 29644573, 2019). "CYLD controls hepatocyte growth factor (HGF) expression in activated HSCs, which in turn affects liver fibrosis and inflammation." (PMID 35579924, 2022).
otorrhea (2 papers, 2010 to 2020). "We also examined the relationships between CYLD/NF-κB and clinical data, such as the presence of active otorrhea and degree of bone destruction, but no such relationships were found in the present study." (PMID 20414373, 2010).
ovarian carcinoma (2 papers, 2016 to 2022). A malignant neoplasm originating from the surface ovarian epithelium. "In contrast, depletion of TRIP6 by TRIP6-specific shRNA or Cas9/sgRNA greatly enhances the association of TRAF6 with A20 and CYLD, and attenuates lysophosphatidic acid-induced muclear factor-κB and JNK/p38 activation in ovarian cancer cells." (PMID 27134758, 2016). "Nonetheless, depletion of TRIP6 by either shRNA or Cas9/sgRNA not only enhanced the association of TRAF6 with A20, but also with CYLD in untreated and treated cells, suggesting a significant role for TRIP6 in antagonizing the binding of TRAF6 to both A20 and CYLD in ovarian cancer cells." (PMID 27134758, 2016). "More importantly, our preliminary data also found that this “double-edged” aspect was not only observed in OSCC, but also in a variety of CYLD-negative malignant cancers, such as triple negative breast cancer, ovarian cancer, and NSCLC (data not shown)." (PMID 36376983, 2022).
parasitemia (2 papers, 2017 to 2025). "Our previous studies have identified CYLD as an inhibitor of immune responses during bacterial and parasitic infections, and inhibition of CYLD resulted in a positive disease outcome." (PMID 39958342, 2025). "Since the parasitemia in Cyld−/− mice was reduced and CD8+ T cells typically play an important role in the control of intracellular pathogens, we determined the influence of CYLD on the CD8+ T cell numbers in the blood during ECM." (PMID 28203236, 2017). "Our study shows that upon both sporozoite and blood-stage infection, parasitemia was detectable in WT and Cyld−/− mice on day 3 p.i., indicating that CYLD deficiency did not prevent parasite replication in the liver." (PMID 28203236, 2017).
pneumonia (2 papers, 2025). An acute, acute and chronic, or chronic inflammation focally or diffusely affecting the lung parenchyma, caused by an infection in one or both of the lungs (by bacteria, viruses, fungi, or mycoplasma.). "Similarly, CYLD impairs inflammation and protects mice from E. coli-induced pneumonia, suggesting that the protective or detrimental function of CYLD in infectious diseases depends on the underlying infection." (PMID 39958342, 2025).
rheumatoid arthritis (2 papers, 2018 to 2024). A chronic, systemic autoimmune disorder characterized by inflammation in the synovial membranes and articular surfaces. "For instance, CYLD downregulation has been shown to enhance the pro-inflammatory effects of rheumatoid arthritis fibroblast-like synoviocytes by activating the NF-κB signaling." (PMID 38561786, 2024).